SOCS3 (suppressor of cytokine signaling 3)
Diseases named in the same sentence as SOCS3 in open-access papers (continued):
Sharing a sentence is not in itself a finding about the gene and the disease.
infection (continued). "This elevated SOCS1 and SOCS3 expression contributes to leptin and insulin resistance in immune cells, impairing their ability to respond to infection effectively." (PMID 40844207, 2025). "A similar mechanism has been described in HIV‐1 infection, where SOCS3 is downregulated early during infection, resulting in enhanced NF‐κB activation and proinflammatory cytokine production." (PMID 40844207, 2025). "Immunofluorescence showed a marked reduction in PCV2-positive cells in SOCS3-silenced groups and enhanced signals in overexpression groups at 36 h post-infection (hpi)." (PMID 40872795, 2025). "S6, D to F), in contrast to other anti-inflammatory genes including Hmox1, Socs1, and Socs3, which were consistently increased in the expression near sites of infection." (PMID 39813329, 2025). "In the context of EBV, the virus upregulates SOCS1 and SOCS3 during latent and lytic phases of infection, likely through viral protein‐induced activation of host STAT3, which enhances SOCS transcription and inhibits downstream antiviral signaling." (PMID 40844207, 2025). "Second, the regulation of inflammatory responses by SOCS3 also affects the infection process of PCV2." (PMID 40872795, 2025). "Compared with the mock-infected controls, the SOCS3 transcript levels showed marked elevations at 24 and 48 h post-infection (hpi)." (PMID 40872795, 2025). "RT-PCR analysis revealed a significant upregulation of SOCS3 mRNA during the early infection stages." (PMID 40872795, 2025). "Although SOCS3 levels increased at 2 h post-infection (p-value = 0.0097), they returned to baseline levels by 4 h post-infection." (PMID 40141288, 2025). "Next, SOCS3 expression was greatly enhanced by infection with lentiviruses carrying SOCS3-overexpressing plasmid." (PMID 38302986, 2024). "In cells incubated with both microorganisms and infected with rotavirus (pre-infection), we observed a significant (p < 0.05) upregulation of the mRNA levels of SOCS3, IFN-γ, STAT1, and IL-10." (PMID 38791551, 2024). "The mRNA levels of all three representative ISGs were elevated in the SOCS3 knockdown versus WT cells at almost every time point during the course of infection." (PMID 39201692, 2024). "Because of its critical role in IL-6 cytokine signaling, SOCS3 has been intensively studied in immune cells and is considered a major regulator of infection and inflammation." (PMID 36753521, 2023). "Even with a very low dose (40 pfu) infection, we observed a 3.6-fold increase of SOCS3 transcription in the infected brains compared with the control at P0, while the high dose led to a much bigger change of 9.5-fold." (PMID 36753521, 2023). "The relative SOCS3 protein levels in HCMV- versus mock-infected NPCs increased dramatically at 4 hours post-infection (hpi) to 4.3-fold, quickly dropped to 2.1-fold at 8 hpi, and then slowly rose to 2.6-fold at 96hpi." (PMID 36753521, 2023). "In MKN1 cells with low SOCS3 expression after T-01 infection, T-SOCS3 showed a more efficient oncolytic effect in a basic research." (PMID 35719333, 2022). "In comparison to fish sampled before infection, il-1β, tnf-α1, tnf-α2, mmp-9, and socs-3 expression shows a trend to reach higher levels in fish sampled on the time frame between 6 and 24 h post-infection." (PMID 35328519, 2022). "Through our previous gene sequencing and qPCR verification, it was proven that the mRNA level of the SOCS3 gene in astrocytes increased significantly at 14dpi and this high expression level persisted until the late stage of infection." (PMID 35296090, 2022). "Given the protective effect of pJAK2 peptide against HuCoV-OC43 infection, we tested if that effect was caused by blunting of the SOCS1 and/or SOCS3 response following the infection." (PMID 35799776, 2022).
infection (continued). "We showed that SOCS3 tyrosine phosphorylation was significantly increased at 24 h post-infection, accompanied by significantly decreased SOCS3 expression in the infected cells." (PMID 34339354, 2021). "For FoBs, immune activation during the first weeks of infection is marked by the upregulation of the IFNγ inducible gene Socs3 and the spleen light zone B cell activation marker CD83." (PMID 34762705, 2021). "Porcine reproductive and respiratory syndrome virus (PRRSV) infection also induces SOCS3 expression through p38/AP-1 signaling pathway to enhance PRRSV replication during infection." (PMID 34568100, 2021). "We found that T. marneffei infection upregulated SOCS3 mRNA expression at 12 h post-infection; however, a down-regulated effect was observed at 24 h post-infection." (PMID 34339354, 2021). "Western blot data depicted increased expression of SOCS1 and SOCS3 protein during infection which further got enhanced in presence of IL6 treatment." (PMID 35011356, 2021). "In the setting of pathogen infection, Tet2 can repress the mRNA expression of suppressor of cytokine signaling 3 (Socs3), a negative regulator of the Janus kinase (JAK)-STAT pathway, promoting the production of myeloid cells and proliferation of immune cells." (PMID 34222235, 2021). "The obtained data signify the anti-inflammatory role of IL6 in establishing SOCS1/SOCS3 immune axis during the early stage of infection." (PMID 35011356, 2021). "After MIA induction by infection, IL-6 in maternal serum is elevated, and placental SOCS3 and CRH are upregulated in response to the increased IL-6." (PMID 34350170, 2021). "MKN1 cells were also infected through T-01 (at MOI of 0.01), T-SOCS3 (at MOI of 0.1), or PBS (–) As a result of Western blot analysis, infection of T-SOCS3 led to increased expression of SOCS3 increased in MKN1 cells." (PMID 33659045, 2021). "During the process of model refinement in this paper, we have identified the ratio of SOCS1:SOCS3 as 3:2 for establishment of infection which is further exploited as a target for designing therapeutics." (PMID 35011356, 2021). "As mentioned, T. gondii infection leads to the suppression of anti-inflammatory IL-6 signals by SOCS3 to control infection." (PMID 33205383, 2021). "To further confirm the function of the Meg3/miR-708/SOCS3 axis in CRC development, we altered the expression of Meg3 and SOCS3, either alone or together, in the colons of ApcminmiR-708−/− mice or Apcmin mice using adenovirus-mediated infection in vivo." (PMID 34934045, 2021). "Herein, the expression of SOCS1 and SOCS3 in the lungs of co-infected mice was much higher than that in individual infection groups and the mock group." (PMID 33968006, 2021). "At the protein level, SOCS3 was significantly decreased by T. marneffei infection at 12 h, 24 h, 48 h post-infection." (PMID 34339354, 2021). "On the other hand, in the present study, one upregualted mRNA (SOCS3), potentially trans-regulated by 32 lncRNAs, was also found to be upregulated during infection with Duck hepatitis A virus type 1 (DHAV-1)." (PMID 32245514, 2020). "Our data reveal that SOCS3 mRNA was already induced within 1 h of infection, whereas SOCS1 and SOCS2 expression was delayed and detectable only after 8 h." (PMID 33023610, 2020). "In conclusion, we demonstrated that H. pylori regulates SOCS3 during early infection and that this process requires an intact T4SS system and TNFα-mediated activation of p38." (PMID 33023610, 2020). "We detected phosphorylated p38 as early as 30 min post-infection, whereas phosphorylation of the canonical SOCS3-inducer STAT3 as well as STAT1 was observed only after 2 h." (PMID 33023610, 2020). "We additionally analyzed SOCS3 expression in cells infected with H. pylori wt or the ΔCagPAI mutant and observed significantly lower SOCS3 mRNA levels upon infection with the mutant compared with the wt strain." (PMID 33023610, 2020).
infection (continued). "Here, we show that human DCs rapidly upregulate SOCS3 expression after infection with wild-type H. pylori P12, whereas the induction of SOCS1 and SOCS2 expression is observed only at later time points." (PMID 33023610, 2020). "Multiple viruses have been shown to increase SOCS3 expression during infection to suppress signal transduction activated by IFNβ." (PMID 32038653, 2020). "Treatment with Brefeldin A results in SOCS3 expression comparable to that observed upon infection with the ΔCagPAI mutant." (PMID 33023610, 2020). "The expression of SOCS1 and SOCS3 genes was quantified by qRT-PCR following MR766 or PRVABC59 infection." (PMID 32120897, 2020). "The expression of Socs1 and Socs3 were analyzed at 12 hours post infection and only the expression of Socs3 was reduced after ZY13 administration." (PMID 32849457, 2020). "Multiple viruses promote their survival by inducing SOCS1 and/or SOCS3 protein expression following infection." (PMID 32192194, 2020). "Our data indicate a specific and strong upregulation of SOCS3 after 1 h of infection, while SOCS1 and SOCS2 displayed delayed kinetics." (PMID 33023610, 2020). "To investigate the role of SOCS3 during H. pylori infection, we performed RNA interference-based silencing of SOCS3 expression prior to infection." (PMID 33023610, 2020). "Taken together, this set of data suggests that only H. pylori wt, but not the ΔCagPAI mutant, is able to induce TNFα expression within 1 h of infection, which in turn activates the expression of SOCS3 mRNA." (PMID 33023610, 2020). "Of note, the increase of SOCS3 in lungs of PR8-infected mice started at 3 h post-infection (hpi) in the early stage of IAV infection." (PMID 31474976, 2019). "The activity of nuclear factor-kappa B (NFκB) and the expression of its target gene IL-6 were suppressed in SOCS3-knockdown A549 cells and the TG mice after infection with IAV." (PMID 31474976, 2019). "IL-6 initiates JAK-STAT signaling cascade and the expression of Suppressor of Cytokine Signaling 3 (SOCS3), a signaling molecule which regulates the immune responses to inflammation and infection." (PMID 31251775, 2019). "In the human amnion cell line FL, this SOCS3 induction occurs very early, within 1 h post-infection (hpi) and coincides with reduction in type I IFN signaling downstream of JAK phosphorylation." (PMID 31031749, 2019). "For the first time, we report that expression of SOCS3 is differentially regulated by HIV-1 during its infection cycle." (PMID 30766526, 2019). "HIV-1 RNA also downregulates the expression of SOCS3 at early stage of infection to promote NF-κB signaling." (PMID 30766526, 2019). "For example, it has been observed that SOCS3 is significantly upregulated by infections with IAV, respiratory syncytial virus (RSV), SARS coronavirus (SARS-CoV), Herpes simplex virus type 1 (HSV-1), or human immunodeficiency virus (HIV)." (PMID 31474976, 2019). "High levels of SOCS3 are also shown in liver specimens from patients with Hepatitis C virus (HCV) genotype 1 infection and chronic Hepatitis B virus (HBV) infection." (PMID 31474976, 2019). "Expression of SOCS1 and SOCS3 were at least 2.5-fold higher in H5N1 virus-infected macrophages than in mock-infected cells at 6-h post infection." (PMID 29475453, 2018). "In summary, we here showed using SOCS3- and STAT3-deficient mice that STAT3 in myeloid cells is detrimental for the control of infection with M. tuberculosis." (PMID 29338039, 2018). "RNA-based next generation sequencing revealed an up-regulation of Il10, Il10rα and further genes involved in IL-10 downstream signaling, including Jak1, Socs3 and Stat3 in the brain upon infection." (PMID 29666403, 2018). "Following low dose infection SOCS3 mRNA was increased in the cecal epithelium, the primary location for egg hatching, and infection, compared to those infected with high dose." (PMID 28508554, 2017).
infection (continued). "Infection of mice with target deletion of SOCS3 in neutrophils and macrophages results in death, as this molecule is upregulated during infection." (PMID 28955329, 2017). "IDO expression was increased following infection (p = 0.05) and there was a trend for increased IDO following loss of SOCS3 in mucosa of uninfected mice, although this was not significant." (PMID 28508554, 2017). "Others have demonstrated that infection of bone marrow-derived macrophages with MCMV passaged through BALB/c-derived MEFs causes an increase in SOCS1 and SOCS3 mRNA expression levels from 2 to 24 hours after infection." (PMID 28182772, 2017). "Treatment of MCMV-infected IC-21 mouse macrophages with the antiviral drug ganciclovir significantly decreases MCMV-stimulated SOCS3 expression at 3 days post-infection." (PMID 28182772, 2017). "Together, SOCS3 restrains an uncontrolled early expression of Arg1 and is necessary for controlling infection of lung macrophages during experimental TB." (PMID 29176982, 2017). "SOCS3 mRNA and protein expression levels were significantly increased in PCV2-infected cells at 72 h post-infection (P < 0.05), indicating that SOCS3 expression was elevated by PCV2 infection in PK-15 cells." (PMID 27581515, 2016). "At 24 h post-transfection, the cells were infected with the PCV2-SH strain at a MOI of 0.05, and at 36 h post-infection, the cells were collected for a Western blotting analysis of SOCS3 and the PCV2 capsid protein." (PMID 27581515, 2016). "Although the suppressor of cytokine signaling (SOCS) genes 1 and 3 were upregulated in the IFN treated cells, only SOCS3 was downregulated in the SAV3 infected cells which points to inhibition of SOCS3 by SAV3 infection in TO-cells." (PMID 27215196, 2016). "SOCS3 can be stimulated by JAK/STAT signaling mediating a feedback inhibition or can be induced via infection by several viruses, including herpes simplex virus 1 (HSV-1), influenza A virus (IAV), and HIV (83, –, 86)." (PMID 27381292, 2016). "Another consequence of an infection by HSV-1 is its capacity to produce the suppressor of cytokine signaling-3 (SOCS3), a host negative regulator of the JAK/STAT pathway, which, in turn, inhibits the IFN-γ capacity to induce phosphorylation of JAK kinases." (PMID 27582741, 2016). "SOCS1 and SOCS3 are required together to prevent the normal interplay of these factors, essential to fight infection and for tissue repair, from escalating into uncontrolled activity and rapid inflammation." (PMID 27583437, 2016). "We previously demonstrated that infection of Huh-7 cells with HCV (JFH1 strain) induces the expression of AXL as well as its downstream target SOCS3." (PMID 26313459, 2015). "From the in vitro studies in SOCS3-deficient macrophages described previously, the opposite outcome would have been predicted – that deletion of SOCS3 would increase M1 gene expression and protect from the infection." (PMID 26579124, 2015). "Our previous studies reported that Lenti-shSOCS3 infection in spinal cord reduced complete SCI-induced mRNA and protein expression of SOCS3, as compared to Lenti-pGipz infection." (PMID 26384335, 2015). "While both chimeric viruses replicated at lower levels than wild type JFH1, both induced significant AXL and SOCS3 up-regulation, albeit more potently following infection with the genotype 1b chimera." (PMID 26313459, 2015). "Other important factors in the IFN pathway are the negative regulators SOCS1 and SOCS3, which increased from 12 h post infection." (PMID 26411318, 2015). "In contrast, when compared to Lenti-pGipz infection, reduction of SOCS3 expression by Lenti-shSOCS3 resulted in longer MAP-2+ dendrites at both 1 and 4 weeks after SCI." (PMID 26384335, 2015). "qPCR analysis showed that shSOCS3 expression by Lenti-shSOCS3 infection led to a significant reduction in IL-6-induced SOCS3 mRNA expression." (PMID 26384335, 2015).
infection (continued). "To further confirm the expression of SOCS3 induced by JEV, we analyzed levels of mRNA and protein of SOCS3 at different time points post infection (p.i.)by semiquantitative RT-PCR and qRT-PCR." (PMID 25390684, 2014). "We here review the latest advances in SOCS3 biology, focusing on its role in the control of infection and inflammation." (PMID 24600449, 2014). "Alike, the infection of human cells by either Epstein–Barr virus or Herpes simplex virus (HSV) has been shown to stimulate SOCS3 expression that suppresses type I IFN production and responses." (PMID 24600449, 2014). "Studies in different mouse models have proven the critical importance of SOCS3 in restraining inflammation and allowing optimal levels of protective immune responses against infections." (PMID 24600449, 2014). "Due to the multiple binding partners of SOCS3, it is hard to predict its role in different infections." (PMID 24600449, 2014). "The role of SOCS3 in the outcome of infection with intracellular bacteria and parasite has also been studied." (PMID 24600449, 2014). "Inflammation and infection stimulate SOCS3 expression in different myeloid and lymphoid cell populations as well as in diverse non-hematopoietic cells." (PMID 24600449, 2014). "Since the LysM promoter is active in neutrophils and SOCS3 has been shown to be a negative regulator of granulopoiesis, we studied whether the increased susceptibility to M. tuberculosis of Socs3fl/fl LysM cre mice was associated to increased numbers of neutrophils at the site of infection." (PMID 23853585, 2013). "First, the role of Socs3 expression in myeloid cells in the control of infection with M. tuberculosis was examined by using Socs3fl/fl LysM cre mice." (PMID 23853585, 2013). "Since IL-6 mediated, at least in part, the inhibition of TNF and IL-12 secretion by SOCS3-deficient BMM and BMDC, the role of IL-6 in the susceptibility of gp130F/F mice to infection with M. tuberculosis was studied." (PMID 23853585, 2013). "Recognition by innate immune receptors was required for SOCS3 expression, since Socs3 mRNA levels after infection were reduced in the Toll-like receptor adaptor molecule MyD88−/− BMM and BMM incubated with a NF-κB inhibitor but not in Irf3−/− BMM." (PMID 23853585, 2013). "SOCS3 expression in T cells reduces the frequency of γδ+ T cells in different organs and the secretion of IL-17 by + T cells in response to infection in a gp130-independent manner." (PMID 23853585, 2013). "SOCS3-deficient BMM showed increased STAT3 activation and diminished secretion of TNF and IL-12 after infection with either M. tuberculosis or BCG." (PMID 23853585, 2013). "Since STAT3 is a major controller of immune and inflammatory responses, we studied the role of SOCS3 in the control of infection with M. tuberculosis." (PMID 23853585, 2013). "We next show that adeno-sh-SOCS3 infection of MC3T3-E1 cells resulted in a significant augmentation of MMP-13 gene expression induced by LPS stimulation when compared with cells infected with control virus (3.8 fold induction vs 53 fold induction, p < 0.001)." (PMID 23638389, 2013). "In the present study, the role of SOCS3 in the outcome of infection with M. tuberculosis was investigated." (PMID 23853585, 2013). "Bone marrow-derived macrophages (BMM) from wild type (WT) mice showed increased accumulation of Socs3 mRNA after infection with either M. tuberculosis or BCG." (PMID 23853585, 2013). "Next, the role of SOCS3 expression by T cells in the control of infection with M. tuberculosis was studied." (PMID 23853585, 2013). "Our data supports such a protective role of SOCS1 and SOCS3 given their much higher levels of expression during late infection phase (45 hpi onward)." (PMID 21901105, 2011). "Increased SOCS expression was also confirmed at the protein level since SOCS1 expression was increased at 60 minutes post-infection whilst SOCS3 expression progressively increased from 20 to 60 minutes post-infection." (PMID 20689596, 2010).